EFNA4-EFNA3 (EFNA4-EFNA3 readthrough )
Gene: Protein-coding gene on chromosome 1 (155,063,748 to 155,086,807, forward strand). Ensembl gene ENSG00000251246.
Genetic constraint (gnomAD): Loss-of-function variants: 14 observed, 23.02 expected, observed/expected ratio (o/e) 0.61, 90% interval 0.4 to 0.95. Missense variants: 311 observed, 315.81 expected, observed/expected ratio (o/e) 0.98, 90% interval 0.9 to 1.08. Synonymous variants: 154 observed, 132.86 expected, observed/expected ratio (o/e) 1.16, 90% interval 1.02 to 1.33.